SNORD14D (small nucleolar RNA, C/D box 14D)
Gene: Small nucleolar RNA gene on chromosome 11 (123,058,909 to 123,058,995, reverse strand). Ensembl gene ENSG00000207118.
Gene Ontology:
Biological process: RNA processing
Cellular component: nucleolus
Homologues: Orthologues: chimpanzee SNORD14 (99% identical), macaque SNORD14 (99% identical), guinea pig SNORD14D (93% identical), pig SNORD14 (92% identical), rat SNORD14 (92% identical), mouse Snord14d (91% identical). Paralogues in human: SNORD14C (79% identical), SNORD14A (71% identical), SNORD14B (69% identical), SNORD14E (67% identical), SNORD14 (61% identical).
Diseases named in the same sentence as SNORD14D in open-access papers:
SNORD14D is named in the same sentence as 1 disease in open-access papers, as found by Europe PMC text mining. Sharing a sentence is not in itself a finding about the gene and the disease. The quoted sentences say what the papers report.
leukemia (1 paper, 2019). A malignant (clonal) hematologic disorder, involving hematopoietic stem cells and characterized by the presence of primitive or atypical myeloid or lymphoid cells in the bone marrow and the blood. "However, other snoRNAs have been shown to act more like oncogenes: indeed, SNORD14D or SNORD35A are required for leukemia development in vivo in certain models." (PMID 31039818, 2019).